AREL1 (apoptosis resistant E3 ubiquitin protein ligase 1)
Description:
E3 ubiquitin-protein ligase that catalyzes 'Lys-11'- or 'Lys-33'-linked polyubiquitin chains, with some preference for 'Lys-33' linkages. E3 ubiquitin-protein ligases accept ubiquitin from an E2 ubiquitin-conjugating enzyme in the form of a thioester and then directly transfers the ubiquitin to targeted substrates. Ubiquitinates SEPTIN4, DIABLO/SMAC and HTRA2 in vitro. Modulates pulmonary inflammation by targeting SOCS2 for ubiquitination and subsequent degradation by the proteasome.
Synonyms: KIAA0317; FIEL1
Tractability: PROTAC: UniProt records ubiquitination sites on it; ubiquitination databases record sites on it.
Gene: Protein-coding gene on chromosome 14 (74,653,437 to 74,713,117, reverse strand). Ensembl gene ENSG00000119682.
Subcellular location (Human Protein Atlas): Vesicles; Cytosol
Pathways (Reactome):
Immune System: Antigen processing: Ubiquitination & Proteasome degradation
Gene Ontology:
Molecular function: protein binding; ubiquitin protein ligase activity; ubiquitin-protein transferase activity
Biological process: negative regulation of apoptotic process; protein K11-linked ubiquitination; protein K33-linked ubiquitination; protein ubiquitination; ubiquitin-dependent protein catabolic process; regulation of inflammatory response
Cellular component: cytosol
Genetic constraint (gnomAD): Loss-of-function variants: 60 observed, 100.68 expected, observed/expected ratio (o/e) 0.6, 90% interval 0.48 to 0.74. The upper end of that interval is the gene's LOEUF score, 0.74, which puts it in group 3 of 6, group 1 being the genes least tolerant of losing a copy. Missense variants: 878 observed, 1,076.6 expected, observed/expected ratio (o/e) 0.82, 90% interval 0.77 to 0.86. Synonymous variants: 380 observed, 398.04 expected, observed/expected ratio (o/e) 0.95, 90% interval 0.88 to 1.04.
Homologues: Orthologues: chimpanzee AREL1 (99% identical), pig AREL1 (98% identical), rabbit AREL1 (98% identical), guinea pig AREL1 (98% identical), rat Arel1 (98% identical), mouse Arel1 (97% identical), dog AREL1 (97% identical), zebrafish AREL1 (81% identical), tropical clawed frog arel1 (68% identical), Drosophila melanogaster CG4238 (48% identical). Paralogues in human: HECTD2 (22% identical), HECW1 (19% identical), NEDD4L (19% identical), HECW2 (18% identical), NEDD4 (17% identical), WWP2 (17% identical), ITCH (17% identical), WWP1 (17% identical), HUWE1 (17% identical), SMURF2 (16% identical), UBE3C (16% identical), SMURF1 (16% identical), and 12 more.
Diseases named in the same sentence as AREL1 in open-access papers:
AREL1 is named in the same sentence as 7 diseases in open-access papers, as found by Europe PMC text mining. Sharing a sentence is not in itself a finding about the gene and the disease. The quoted sentences say what the papers report.
cancer (1 paper, 2026). A tumor composed of atypical neoplastic, often pleomorphic cells that invade other tissues. "AREL1 acts as a general inhibitor of apoptosis in cancer cells induced by various stimuli." (PMID 41511368, 2026).
AREL1 also shares sentences with these, for which no sentence is quoted: depression (1 paper); idiopathic pulmonary fibrosis (1); infection (1); lung fibrosis (1); multiple system atrophy (1); Stroke (1).